CXorf51B (chromosome X open reading frame 51B)
Synonyms: CXorf51A
Tractability: No criterion of Open Targets' tractability assessment is met for any kind of drug.
Gene: Protein-coding gene on chromosome X (146,809,771 to 146,810,411, forward strand). Ensembl gene ENSG00000235699.
Gene Ontology:
Molecular function: protein binding
Homologues: Orthologues: chimpanzee CXHXorf51B (99% identical). Paralogues in human: CXorf51A (100% identical).